ASB12 (ankyrin repeat and SOCS box containing 12)
Description:
Probable substrate-recognition component of a SCF-like ECS (Elongin-Cullin-SOCS-box protein) E3 ubiquitin-protein ligase complex which mediates the ubiquitination and subsequent proteasomal degradation of target proteins.
Synonyms: FLJ39577
Tractability: PROTAC: ubiquitination databases record sites on it.
Gene: Protein-coding gene on chromosome X (64,224,194 to 64,230,607, reverse strand). Ensembl gene ENSG00000198881.
Pathways (Reactome):
Immune System: Antigen processing: Ubiquitination & Proteasome degradation
Metabolism of proteins: Neddylation
Gene Ontology:
Molecular function: protein binding; ubiquitin protein ligase activity
Biological process: protein ubiquitination
Cellular component: ubiquitin ligase complex; cytosol
Homologues: Orthologues: chimpanzee ASB12 (99% identical), macaque ASB12 (99% identical), rabbit ASB12 (94% identical), pig ASB12 (92% identical), guinea pig ASB12 (90% identical), rat Asb12 (86% identical), mouse Asb12 (86% identical), zebrafish asb12b (58% identical), tropical clawed frog asb12.2 (57% identical), zebrafish asb12a (53% identical), tropical clawed frog asb12 (47% identical). Paralogues in human: ANKRD29 (24% identical).
Diseases named in the same sentence as ASB12 in open-access papers:
ASB12 is named in the same sentence as 4 diseases in open-access papers, as found by Europe PMC text mining. Sharing a sentence is not in itself a finding about the gene and the disease. The quoted sentences say what the papers report.
glioma (1 paper, 2025). A benign or malignant brain and spinal cord tumor that arises from glial cells (astrocytes, oligodendrocytes, ependymal cells). "However, the clear connection between ASB12 and glioma is yet to be established." (PMID 40319095, 2025).
tumor (1 paper, 2025). "As expected, ASB12 mRNA was highly expressed in tumor tissues (cohort 4) of BCa patients, as well as in BCa cell lines." (PMID 40297540, 2025). "Our study revealed that ASB12 could promote tumor cell proliferation and migration and reduce cell cycle arrest as well as cell apoptosis in BCa cells." (PMID 40297540, 2025).
ASB12 also shares sentences with these, for which no sentence is quoted: bladder cancer (1 paper); cancer (1).